IL5 (interleukin 5)
Diseases named in the same sentence as IL5 in open-access papers (continued):
Sharing a sentence is not in itself a finding about the gene and the disease.
asthma (continued). "A study has found that there were reduced levels of Th1 in asthma, which reduces the levels of certain Th1-secreted cytokines including IFN-γ, and elevated levels of Th2, which can produce large amounts of IL-4, IL-5, and IL-13." (PMID 36846048, 2023). "Estrogens and progesterone affect the immune response and pathogenesis of asthma, airway hyperresponsiveness, and type 2 inflammation involving eosinophils, ILC2, IL-13, and IL-5." (PMID 37629446, 2023). "Biologic agents targeting inflammatory cytokines, comprising anti-immunoglobulin (Ig)E and anti-interleukin (IL)-4/IL-13, IL-5, IL-5R, and thymic stromal lymphopoietin (TSLP) have emerged as promising treatment options for patients with severe asthma." (PMID 36845128, 2023). "In this study, sputum IL-5 was measured by an ELISA kit and SERS biosensor in 10 subjects with asthma." (PMID 38149176, 2023). "In BALB/c-OVA model of asthma, the HIF-1α antagonist YC-1 suppressed HIF-1α expression and lowered the transcript levels of IL-5, IL-13, myeloperoxidase, and NOS2." (PMID 35453294, 2022). "In the HDM-induced mouse asthma model, we found that the HDM extract promoted airway hyperresponsiveness (AHR), MUC5AC, and allergen-specific IgE production as well as IL-5 and IL-13 for recruiting inflammatory cells." (PMID 36012669, 2022). "CAD significantly decreased the content of TNF-α, IL-13, IL-4, IL-1β and IL-5 in the bronchoalveolar lavage fluid (BALF), IL-17, IL-6, and OVA-specific IgE in serum and increased serum IFN-γ in asthma mice." (PMID 36213326, 2022). "In an experimental asthma rat model, CBD diminished airway inflammation and IL-4, IL-5, IL-13, IL-6, IL-7 and TNF-α serum levels, which contribute to fibrosis and asthma pathophysiologies." (PMID 36556483, 2022). "In this study, although IL-4 levels were under the detection threshold and IL-13 levels were low in patients with ABPA, their IL-5 levels were significantly higher than those in patients with CPA and were the second-highest after those in patients with asthma." (PMID 35628692, 2022). "One cell type that also produces IL‐5 and IL‐13 in response to IL‐33 is the mast cell, and as TGF‐β has been shown to suppress IL‐33–induced mast cell function in the context of asthma, this population is a prime candidate for further investigation." (PMID 35758054, 2022). "IL‐4, IL‐5 and CCL26 were significantly higher in T2‐high‐FNS compared with both T2‐low asthma and healthy controls." (PMID 35579040, 2022). "Here we therefore aim to appraise the available evidence for the effect of anti-IgE, anti-IL5 (Rα), anti-IL4Rα, anti-TSLP and anti-IL33 biologics on small airways disease in patients with severe asthma." (PMID 36239786, 2022). "It is well-known that IL-4, IL-5, and IL-13 cytokines produced by CD4+ natural killer T cells and CD4+ T MHCII-restricted cells enhance eosinophilia and increase the severity of asthma." (PMID 35733161, 2022). "VD supplementation improved the indicators of asthma and COPD, especially in pulmonary function, SGRQ scores, IL-5, and IgE." (PMID 36520525, 2022). "The major flavonodial compound in the extract (vitexin) was shown to reduce the levels of inflammatory cytokines such as IL4, IL5, and IL13 by 64%, 95%, and 65% in an induced asthma model at concentration of 1 mg/kg." (PMID 35050106, 2022). "IL‐5, CCL17, CCL26 and TSLP concentrations were elevated significantly in asthma overall compared with health." (PMID 35579040, 2022). "AYC-EV (8 mg/kg)-treated asthma-induced mice (G4) showed decreased levels of IFN-γ+CD4+, IL-5+CD4+, IL-17A+CD4+, and IL-5+IL-17A+CD4+ T cells as compared to the disease-causing groups (G2)." (PMID 36139376, 2022). "In our HDM-induced asthma model, we found that PEP-NASP peptide treatment markedly ameliorated AHR and reduced the production of type two inflammatory cytokines (IL-5 and IL-13) and MUC5AC." (PMID 36012669, 2022).
asthma (continued). "We found the severe asthma cohort had overall increased levels of TSLP (median values, pg/mL, 0.409 vs. 0.923, p = 0.016) and IL-5 (median values, pg/mL, 0.248 vs. 0.940, p = 0.016) compared to the mild/moderate asthma group." (PMID 36245744, 2022). "Therapies targeting mast cell mediators and/or their receptors, including monoclonal antibodies targeting IgE, IL-4/IL-13, IL-5/IL-5Rα, IL-4Rα, TSLP, and IL-33, have been found safe and effective in the treatment of different phenotypes of asthma." (PMID 36430941, 2022). "In asthma, allergic airway inflammation is initiated by IL-33 signaling through ST2, leading to increased IL-4, IL-5, and IL-13 production and eosinophil infiltration." (PMID 35025767, 2022). "In fact, mepolizumab and benralizumab, which are humanized monoclonal antibodies targeting IL-5 and IL-5Rα, respectively, have both shown remarkable therapeutic effects in various types of eosinophilic diseases, including ECRS and asthma." (PMID 36016937, 2022). "CRSwNP endotype markers with nasal polyposis indicate the desirability of using biological medicines targeting these receptors (IgE, IL-4, IL-5, and IL-13), especially in the treatment of CRS with nasal polyps and asthma (IL-5)." (PMID 35740420, 2022). "The levels of IL-4, IL-5, IL-13, IFN-γ, eotaxin, and IgE in the asthma group were significantly higher than those in the control group." (PMID 35990822, 2022). "The asthma exacerbation (AE)-free time of the FeNO/B-EOS subgroups and any biologics treatment including anti-IgE or anti-IL-5 use were examined using the Kaplan–Meier method." (PMID 35517829, 2022). "The level of production of IgE, IL-4, IL-5, IL-13, and IFN-γ is related to the severity of asthmatic symptoms in T2 asthma." (PMID 36430662, 2022). "Anti-IL-5 monoclonal antibodies -mepolizumab and reslizumab- were approved by EMA for severe asthma with peripheral eosinophilia in 2015 and 2016, respectively." (PMID 35203504, 2022). "Another mediator secreted by eosinophils when activated by IL-5 is transforming growth factor-β1 (TGF-β1), which significantly concurs to airway remodeling in severe asthma via its fibrogenic effects." (PMID 35625801, 2022). "In T2-high asthma, clinical symptoms result from inflammation driven by the cytokines interleukin-4 (IL4), IL5, and IL13, as well as alarmins [thymic stromal lymphopoietin (TSLP), IL25, IL33] and Immunoglobulin E (IgE)." (PMID 36237537, 2022). "Consistently, we detected IL-4, IL-5, IL-13, IL-25, IL-10, IL-33, and TSLP in induced sputum of asthma and proved a positive correlation between BIRC3 and these cytokines." (PMID 35287655, 2022). "For example, IL-5+ ILC2 in peripheral blood and sputum of severe asthma patients is increased as compared to those with mild asthma or control patients." (PMID 35795686, 2022). "Asthma is an inflammatory disease characterized by AHR, the production of Th2 inflammatory cytokines (IL-4, IL-5, and IL-13), and the increased infiltration of inflammatory cells into the airways that results from the activation of Th2 cells." (PMID 36311189, 2022). "Therapeutic approaches targeting IL-4, IL-5, and TNF-α through their selective inhibitors are under clinical trials in management of asthma." (PMID 38143476, 2022). "They found IL-5 and IL-13 producing CD34+ stem cells were present in the sputum of patients with asthma, and increased after allergen challenge." (PMID 36177009, 2022). "In Th2-high asthma, MAPK promotes Th2 cells to release IL-4, IL-5, and IL-13, stimulating IgE production, eosinophil recruitment, and airway hyperresponsiveness." (PMID 35447890, 2022). "IL-4, IL-5, and IL-13 in BALF were measured to be about 10 times greater following the induction of asthma by OVA as compared to normal mice." (PMID 36115955, 2022).
asthma (continued). "In order to explore the relationship between the expression of IL1-RL1 in sputum supernatant of patients with asthma and type 2 inflammation, we analyzed the correlation between IL1-RL1 and Th2 inflammatory factors, such as IL-4, IL-5, IL-10 and IL-13." (PMID 35578178, 2022). "Corni Fructus has been reported to reduce IL-5, CCL11, and OVA-specific IgE and inhibit eosinophil infiltration in the OVA-induced asthma model." (PMID 35887796, 2022). "Increased release of Th2 cytokines mainly IL-4, IL-5, and IL-13 and decreased release of IFN-γ as a Th1 cytokine also contribute in the onset and progression of asthma." (PMID 34804178, 2021). "Asthma is believed to be mediated by CD4+ T-lymphocytes, which produce type 2 cytokines including IL4 and IL5." (PMID 33918602, 2021). "One asthma exacerbation requiring OCS occurred in each the anti‐IgE and anti‐IL4R group and one CRSwNP exacerbation in the anti‐IL5/R group." (PMID 34331521, 2021). "Examination of cytokine profiles from phase 1 demonstrated differences potentially suggestive of an asthma/allergy phenotype in mothers of ASD children, with elevated concentrations of IFN-γ, IL-4 and IL-5." (PMID 33736683, 2021). "miR-224 plays an inhibitory role in PM2.5-induced asthma by inhibiting Th17 and TLR2, resulting in reduced secretion of IL-17, IL-4, and IL-5." (PMID 34566492, 2021). "Given the similarity between asthma and COPD in terms of eosinophilic airway inflammation, several randomized controlled trials (RCTs) have studied the efficacy and safety of anti-IL-5 treatment in eosinophilic COPD patients." (PMID 34795588, 2021). "Recently, much attention has been dedicated to IL-5- and IL-13-producing ILC2 significantly increased in sputum of patients with severe asthma with uncontrolled eosinophilia despite treatment with high-dose oral corticosteroids (OCS)." (PMID 33805199, 2021). "In asthma, type III Interferons have been reported to decrease IL-4 and IL-5 production, as well as IL-13 production by T cells providing evidence for a protective role in asthma exacerbations." (PMID 34899691, 2021). "The biomarkers suspected to be most indicative of asthma are related to inflammation (type 2) and are attributed to TH2-cytokines, IL-4, IL-5, and IL-13." (PMID 34712855, 2021). "PBM presents significant and effective results in the reduction of eosinophils, production of IL-4, IL-5, and IL-13 in BAL, airway remodeling, and lung function in asthma." (PMID 35185864, 2021). "The standard of care for allergic asthma consists of inhaled corticosteroids and short- and long-acting bronchodilators, which control asthma symptoms in the majority of patients, complemented by anti-IL4 and anti-IL5 pathway therapies." (PMID 33918602, 2021). "CP and OA were shown to significantly inhibit airway and lung inflammation, mucus secretion, lymphocytes, neutrophil and eosinophil infiltration, AHR, and inflammatory mediators such as IL-5, IL-13, CCR3, MUC5AC, and COX-2 in the mouse model of asthma." (PMID 33806085, 2021). "This function is in addition to the known roles of PI3Kδ in allergic asthma such as; leucocyte migration into inflamed tissues, release of asthma relevant cytokines (IL4 and IL5) and chemokines (RANTES and eotaxin)." (PMID 34920698, 2021). "IL-5 and IL-13 showed strong correlations with AHR and CCL2 (MCP-1) in asthma severity and fast lung function decline." (PMID 33806085, 2021). "In the pathogenesis of asthma, CD4+ T cells synthesize proinflammatory cytokines such as IL-4, IL-5 and IL-13." (PMID 34209324, 2021). "For example, murine eosinophils can present antigen via MHC class II and promote IL-4, IL-5, and IL-13 production from antigen-specific CD4+ T cells in the context of helminth infection or asthma." (PMID 34733292, 2021). "Group 2 ILC (ILC2) secrete interleukin (IL)-5, IL-9 and IL-13 in response to IL-25 and IL-33 stimulation, and circulating ILC2 levels are increased in adults with asthma." (PMID 34220812, 2021).
asthma (continued). "Type 2-driven asthma is a subtype of asthma in which there is a notable release of interleukin-4 (IL4), IL5, and IL13 from cells of both innate and adaptive immune systems." (PMID 34575604, 2021). "Asthma is driven by group 2 innate lymphoid cells, antigen-specific CD4+ T helper type 2 cells and their cytokines such as interleukin (IL)-4, IL-5, IL-13." (PMID 34516405, 2021). "There was a report that ILC2s were a major production source of Il-5 and IL-13 in an OVA-induced asthma mouse model." (PMID 32397396, 2020). "Our findings open up the possibility of using anti-IL-5 monoclonal antibodies for the management of ACO, similar to that of the treatment suggested for severe asthma." (PMID 32448302, 2020). "Th2 responses in the STAT6KO Treg-of-B (P) group, including OVA-specific IgE and IgG1, IL-5 produced by splenocytes, eotaxin in BALF, airway hyperresponsiveness and infiltrated eosinophilia in BALF, were all comparable with those in the asthma group." (PMID 33584704, 2020). "An earlier study also reported that fucoidans isolated from U. pinnatifida sporophylls attenuated the Th2 response via suppressing Th2 cytokines (IL-4, IL-5, IL-13) in an OVA-induced mouse model of asthma." (PMID 32580518, 2020). "Animal models of asthma have indicated that the expression of the clock gene BMAL1 plays a role in eosinophil trafficking and the production of the cytokine IL-5, which is a target of multiple asthma drugs and has been shown to be under epigenetic regulation." (PMID 32662059, 2020). "In a mouse model of asthma, suppression of HIF‐1α with YC‐1 reduced expression of IL‐5, IL‐13, myeloperoxidase (MPO) and inducible nitric oxide synthase (iNOS), which alleviated asthma symptoms." (PMID 32633061, 2020). "The renowned type-2-high immunity occurs in almost half of asthma patients, manifested as features of eosinophilia, AHR, the elevation of IL-4, IL-5, IL-13, and Ig E in lung and blood." (PMID 33013383, 2020). "They effect Th2 cell function either directly or via innate lymphoid cells (ILCs), which in turn produce IL-5, IL-9, and IL-13, related to Th2-type CRS, asthma and AR." (PMID 32292784, 2020). "The expression of IL-5, a pro-inflammatory Th2 cytokine, was highest in patients with ACO as compared to asthma, COPD and controls." (PMID 32448302, 2020). "In 30 patients (71%) in the anti-IL5/IL5R group and in 10 patients (45%) in the anti-IgE group asthma treatment involved continuous OCS prior to biological therapy." (PMID 32467765, 2020). "We collected and analysed results of anti-IL5/IL5R and anti-IgE therapies for asthma from January 2009 until October 2019 in specialized care." (PMID 32467765, 2020). "You22 detected some cytokines in bronchoalveolar lavage fluid (BALF) in asthma model, and OVA and DEHP participated a salient Th2 response which was characterized by the upregulation of Th2-type cytokines, such as IL-4, IL-5 and IL-13." (PMID 32884073, 2020). "In fact, these results are in agreement with another study where RSV (100 mg/kg body weight) was found to reduce IL-5 and IL-13 expressions in mice with OVA-induced asthma." (PMID 33013379, 2020). "In conclusion, we offer an anti–IL-5Rα humanized Ab, 5R65.7, which more potently inhibits IL-5–dependent eosinophil proliferation and induces NK cell–mediated ADCC against eosinophils from patients with severe asthma, as compared with a benralizumab analogue." (PMID 33488590, 2020). "Before biological therapy, 41 patients (98%) in the anti-IL5/IL5R group used long acting beta agonist (LABA) daily and 35 patients (83%) used two or more asthma controllers, in addition to ICS, on a daily basis." (PMID 32467765, 2020). "Similar to 6A4G7, 17A1D10 inhibited D. pteronyssinus or Der p 2-stimulated IL-5 and IL-13 production in the MoDC/CD14− PBMC co-cultures of patients with asthma (respectively)." (PMID 31861989, 2019).
asthma (continued). "The results of one-way ANOVA revealed that IL-5 levels differed significantly between the PBMC culture and P+S coculture (different MSC concentrations) in the asthma group (F = 13.59, degrees of freedom = 142, P < 0.0005)." (PMID 31673233, 2019). "It is also worth noting that among the included agents, only dupilumab and the three IL-5 pathway agents (mepolizumab, reslizumab and benralizumab) are currently FDA approved for severe asthma." (PMID 31395084, 2019). "Higher levels of several Th2 cytokines have been found in BAL of asthmatics, including IL-4, IL-5, IL-13, IL-25, IL-33, and TSLP, and the levels of Th2 cytokines correlate with severity of asthma exacerbation." (PMID 30764493, 2019). "In this study, we demonstrated that anti-Dectin-2 MoAbs considerably inhibit HDM-induced IL-5 and IL-13 production in DC- and monocyte-depleted PBMC co-cultures of patients with asthma." (PMID 31861989, 2019). "IL-5 levels differed significantly between the PBMC culture and P+S coculture in both the lower (P < 0.05) and higher (P < 0.0005) IgE asthma subgroups." (PMID 31673233, 2019). "Basic and clinical studies have revealed that IL-5 is essential for the development of BHR, at least in Th2 cell-mediated asthma, by reducing allergen-induced airway eosinophilic inflammation via its neutralizing antibody." (PMID 31216735, 2019). "IL-5 levels differed significantly between the PBMC and P+S coculture and among the children with asthma who had mild (P < 0.05), moderate (P < 0.05), severe (P < 0.05), and extremely severe (P < 0.05) asthma symptom scores." (PMID 31673233, 2019). "The anti-IL-25 antibody significantly reduced the levels of IgE, IL-5, and IL-13; goblet cell hyperplasia; and eosinophil infiltration, and prevented AHR in murine asthma models." (PMID 31284537, 2019). "The humanized anti-IL-5 antibody mepolizumab improves FEV1 and reduces the number of eosinophils in the sputum and blood in asthma." (PMID 31284537, 2019). "As with anti-IL-5 antibodies, dupilumab was assessed regarding its efficacy in reducing OCS in asthmatics with oral steroid-dependent asthma." (PMID 31480806, 2019). "The precursors of ASHMI, MSSM-002, inhibit Group 2 cytokines (the inhibition of IL-4, IL-5, IL-13, and GATA-2 and the enhancement of IFN-γ expression) to relieve asthma symptoms." (PMID 31284537, 2019). "DA treatment effectively inhibited methacholine responsiveness, inflammatory cell infiltration, proinflammatory cytokines such as interleukin (IL)-5 and IL-13, and immunoglobulin (Ig) E in OVA-induced asthma model." (PMID 30991656, 2019). "In asthma, the paradigm of allergic disease, the cytokine profile in BAL shows elevation of IL-4, IL-5, and IL-9 compared to control groups." (PMID 31772507, 2019). "IL-5 levels significantly differed between the PBMC culture and P+S coculture in both the lower and higher IgE asthma subgroups (P < 0.05)." (PMID 31673233, 2019). "IL-5 levels differed significantly between the PBMC culture and PBMC + MSC (P+S) coculture in the asthma group (P < 0.05)." (PMID 31673233, 2019). "The antiasthma simplified herbal medicine intervention (ASHMI) alleviates asthma symptoms by modulating Group 1 cytokine (inhibition of TNF-α and IL-6) and Group 2 cytokine (inhibition of IL-17, IL-13, IL-5, and IL-4, and enhancement of IFN-γ) expression." (PMID 31284537, 2019). "In murine models of asthma, CD4+ T-helper cells in the lungs and bronchoalveolar lavage fluid decrease eosinophilia and the Th2 cytokine secretion of IL-4, IL-5, IL-13, and TGF-β." (PMID 29959403, 2018). "We found that the frequencies of GATA3+IL-4+, GATA3+IL-5+, and GATA3+IL-13+ CD4+ T-cells in the lungs of asthma-induced Bcl11bfl/fl dLck-iCre mice were reduced, as were the frequencies of GATA3+, IL-4+, IL5+, and IL-13+ CD4+ T-cells." (PMID 29700302, 2018).